EGFR (epidermal growth factor receptor)
Diseases named in the same sentence as EGFR in open-access papers (continued):
Sharing a sentence is not in itself a finding about the gene and the disease.
tumor (continued). "Taken together, these observations strongly support out hypothesis, that EGFR-mediated tyrosine phosphorylation of GPRC5A inactivates some of the tumor suppressor activities of GPRC5A." (PMID 25311788, 2014). "Therefore, anti-EGFR monoclonal antibodies are only indicated in patients with KRAS wild-type tumours." (PMID 24720724, 2014). "Interestingly, in all tested biopsies EGFR+ tumour cells displayed a significantly higher DI than stromal haematopoietic cells (CD45+/CD44+)." (PMID 24154962, 2014). "Routine EGFR testing gives a qualitative analysis of EGFR mutations, tumor is either mutated or non-mutated and the proportion of mutated allele is not taken into consideration." (PMID 24885034, 2014). "EGFR is activated in tumor-associated endothelial cells, but not in endothelial cells within uninvolved organ regions, suggesting that EGFR activation and expression is partially determined by the tumor microenvironment." (PMID 25566498, 2014). "In such case, EGFR high cells may have yet undefined properties, such as paracrine effects on the major tumor cell population or features of cancer stem cells." (PMID 24940619, 2014). "Moreover, EGFR signaling is important in normal epithelial development and in tumor cell proliferation, motility, survival and metastasis and it is known to be overexpressed in BCs, especially in triple negative BC cases." (PMID 25277187, 2014). "Since EGFR inhibitor plays a detrimental role in tumor proliferation, it would be assumed that the decreased number of tumor cell could affect the immune reaction because of the lesser antigen." (PMID 25240937, 2014). "EGFR stimulation by its ligands occurs in an autocrine, paracrine or juxtracrine manner, triggering signaling pathways involved in proliferation, survival, migration, invasion and angiogenesis of primary brain cells, including tumor-initiating cells." (PMID 24709958, 2014). "It has been hypothesized that these results may be due to a decrease in tumor vasculature mediated through endothelial apoptosis, given that EGFR is expressed not only on tumor cells but also on dividing endothelial cells." (PMID 24624093, 2014). "Applying a combination of X-rays or chemotherapy and EGFR-targeting drugs of low general toxicity may enhance the lethal effect of local irradiation and/or revert tumor resistance." (PMID 24295852, 2014). "EGF and its receptor EGFR serve as a paradigm for signaling in cell, molecular and tumor biology." (PMID 25184905, 2014). "In tumor cells, integrin β4 can relocate from hemiodesmosomes to the leading edge of migrating cells where it is involved in the signaling of many receptor tyrosine kinases, including ErbB2, ErbB3, EGFR and Met." (PMID 24885350, 2014). "Inhibition of EGFR enhanced T cell function and improved survival of tumor-bearing mice." (PMID 24722523, 2014). "Various cytosolic and membranous EGFR immuoreactivities, together with nuclear and faint cytosolic C/EBPβ immuoreactivities, and cytosolic and nuclear miR-31 staining, were seen in the tumor tissues." (PMID 25229239, 2014). "HER-2 and EGFR are transmembrane tyrosine kinases that can promote tumour genesis and progression." (PMID 24454858, 2014). "However, in his talk, Marais focused on how epidermal growth factor receptor (EGFR) up regulation and mutations in other kinases can drive resistance to B-Raf inhibitors in tumours with this mutation." (PMID 24482671, 2014). "In gastric cancer, activation of STAT3 via the EGFR signaling pathway may contribute to tumor progression by increasing lymph node metastasis of the tumor." (PMID 24662939, 2014). "Tumor cells were negative for wild-type of epidermal growth factor receptor/K-RAS variants; thus, she was not eligible for tyrosine kinase inhibitor therapy." (PMID 24885608, 2014).
tumor (continued). "The emerging diurnal regulation of EGFR activity by GR suggests that tumour progression driven by aberrant forms of RTKs is strongly suppressed during the active phase of the day, but it might reach full impact during the resting phase, when GC levels are low." (PMID 25278152, 2014). "Aggressive tumor biology and corresponding poorer prognosis is associated with amplification or overexpression of HER2, a transmembrane tyrosine kinase protein belonging to the human epidermal growth factor receptor (EGFR) family of proteins." (PMID 24708527, 2014). "Together, our findings suggest that adding chloroquine to EGFR and AKT inhibition has the potential to improve tumor responses in EGFR M+ NSCLC, and that selective targeting of AKT2 may provide a new treatment option in NSCLC." (PMID 24946858, 2014). "The present study aimed to investigate whether the expression of EGFR and/or c-Kit, in tumor tissue samples from patients who had undergone surgery for NSCLC, was capable of predicting patient survival." (PMID 25013472, 2014). "In addition, we evaluated the efficacy of this panel of four EGFR/cMET pathway inhibitors to block the migration of four of the eight lung tumor cell lines in tumor spheroids." (PMID 24638075, 2014). "We found that EGFR copy number was heterogeneous between different fragments from the same tumor." (PMID 24885034, 2014). "In anti-EGFR resistant tumours showing this profile further alternate signalling mechanisms may be employed, including continued signalling via Met by driving HER3 dependent activation of PI3K." (PMID 24964744, 2014). "The EGFR mRNA expression levels were evaluated in fresh-frozen tumor samples from 129 patients." (PMID 24629097, 2014). "As an example, tumor BI15 was called as amplified for EGFR in two out of five regions with no other somatic mutations/point mutations detected across the tumor." (PMID 25608559, 2014). "To date, no effective biomarker is currently available for patients with wild-type EGFR tumor." (PMID 25410981, 2014). "IF was performed to detect phosphorylated (p)-EGFR and nuclear C/EBPβ in tumor tissues." (PMID 25229239, 2014). "We next assessed whether the increased EGFR activity is also functionally required for the tumour growth-promoting effect of PHD3 inactivation in vivo." (PMID 25420773, 2014). "Some studies have reported that serum levels of MUC1 (mucin 1, also called KL-6) and vascular endothelial growth factor (VEGF) are associated with tumor response, progression-free survival (PFS) and overall survival (OS) in NSCLC patients treated with EGFR-TKIs." (PMID 25410981, 2014). "BMS-690514, a reversible oral inhibitor of EGFR, HER-2 and −4, VEGFRs-1 to −3, showed antitumour activity in tumour xenograft models and in cell lines containing the EGFR T790M mutation, suggesting a role against erlotinib-resistant tumours." (PMID 25505694, 2014). "This indicates that PR and EGFR may have significant roles in tumor progression during NNK-induced mouse lung carcinogenesis." (PMID 25364399, 2014). "The results of the present study expand the existing repertoire of CDK-independent activities of p27Kip1, and suggest that the increased cell-cycle transition due to p27Kip1 deficiency can synergize with increased expression of growth-promoting signals (e.g. EGFR) to accelerate tumour progression." (PMID 25121353, 2014). "Discontinuation of EGFR-TKI may lead to rapid tumor regrowth and many patients developed asymptomatic or slowly progressing disease." (PMID 25563355, 2014). "Strikingly, TGF-β receptor inhibitor abrogated motility of erlotinib-resistant tumor cells suggesting that cytokines might be promising target to overcome EGFR inhibitor resistance." (PMID 25240937, 2014).
tumor (continued). "Another use is for genetic analysis including gene expression analysis of tumor biomarkers such as HER2/E-cadherin by qRT-PCR, and mutation analysis of oncogenes/suppressor oncogenes such as EGFR/KRAS by PCR-based whole genome amplification (WGA) and subsequent direct sequencing." (PMID 24523941, 2014). "The inconsistent status of EGFR mutations, also called heterogeneity, is believed to be associated with the secondary mutation of tumor cells, or to have existed during the transformation of a normal cell to a cancerous cell." (PMID 25295096, 2014). "However, few studies have evaluated the efficacy of EGFR-TKIs focusing on metastatic sites as a tumor property." (PMID 25364452, 2014). "At FISH analysis, 3/113 (2.7%) tumours showed EGFR amplification." (PMID 24867389, 2014). "and iiii- is EGFR copy number heterogeneous within the tumor?" (PMID 24885034, 2014). "Tumor-specific markers such as the EGFR and HER-2 genes have also been utilized to detect CTCs." (PMID 25521853, 2014). "Erlotinib inhibits the activity of EGFR mutation-negative NSCLC tumor cells at a 50% inhibitory concentration of 2–20 nmol/l." (PMID 25364452, 2014). "PCR-based DNA sequencing analysis of the patient’s tumor specimen revealed no EGFR, BRAF, KRAS, PI3KCa, or c-kit mutations." (PMID 25126591, 2014). "Moreover, women with EGFR mutant tumor treated with front-line CT and salvage anti-EGFR TKI showed a trend toward a better OS in comparison with those affected by EGFR wild-type tumor undergoing the same sequence (HR 0.560; p = 0.131)." (PMID 25300933, 2014). "In recent years, EGFR has become a promising target for therapies against various tumor entities." (PMID 24457059, 2014). "In this study, we showed that EGFR inhibition augmented PGE2 production by Sa-3 tumor cell, and that COX-2 inhibitor could restore the suppression of antigen-specific CD4+ T cell responses." (PMID 25240937, 2014). "Indeed results depend on the estimation of the tumor cell content, on the method’s detection cut-off and on EGFR copy number." (PMID 24885034, 2014). "Hence, identification of novel receptors expressed in tumor cells that target against EGFR activation will be a promising strategy against NSCLC." (PMID 24811863, 2014). "EGFR overexpression is also correlated with large tumor size, aggressiveness and poor prognosis." (PMID 24886365, 2014). "Thus, GBM tumor cell proliferation is substantially less sensitive to ECM stiffness when EGFR signaling is reduced, implying that matrix stiffness acts in part through EGFR-mediated signaling pathways to promote proliferation." (PMID 25000176, 2014). "This indicates that PR and EGFR may exhibit significant roles in tumor progression during NNK-induced mouse lung carcinogenesis." (PMID 25364399, 2014). "Although the mutation status of EGFR and KRAS are used as predicting biomarkers for EGFR targeted therapy in other tumor types, their (extremely) low prevalence in HNSCC will likely preclude a major role in helping to define treatment options in these patients." (PMID 24899223, 2014). "The minimum tumor cell count that allowed for successful EGFR testing in this series was 100 cells." (PMID 25295226, 2014). "Furthermore, changes that make Ras hyperactive result in tumours that are resistant to anti-EGFR therapies given that Ras appears downstream of EGFR." (PMID 25228915, 2014). "Published data demonstrates that EGFR plays an important role in tumor progression." (PMID 24816687, 2014). "The cross-talk between EphA2 and EGFR signalling supported evidence that simultaneously inhibiting both EphA2 and EGFR overexpression may provide better anti-tumor response." (PMID 24495444, 2014).
tumor (continued). "The results suggest that RAK may have elevated tumor suppressive activity in tissues expressing mutant EGFR." (PMID 25594057, 2014). "Our results also show that internalization of the EGFR can differ depending on which ligand is bound, and further stress the importance of determining the identity of the ligands present in a tumor environment when studying and predicting EGFR signaling and regulation." (PMID 23472148, 2013). "Subsequently, doses of 75-150 mg/kg have been shown to result in tumour growth inhibition in a range of human tumour xenograft models including tumours that are PIK3CA mutant, PTEN null, EGFR mutant or wild type, with an associated decrease in AKT and S6 phosphorylation." (PMID 24339963, 2013). "Analysis of the EGFR L858R substitution by PCR–ASP and PNA–LNA PCR clamp techniques led to concordant identification of this mutation in 50 % (3/6) of CNS samples and in a corresponding sample from a primary tumour." (PMID 23892415, 2013). "Here, we summarize the mechanisms by which tumors resist EGFR-targeted therapies and highlight the emerging role of microRNAs (miRs) as downstream effector molecules utilized by EGFR to promote tumor initiation, progression and that play a role in resistance to EGFR inhibitors." (PMID 24349829, 2013). "High expression levels of EGFR and Ki-67 were observed in the A431 tumor." (PMID 24191959, 2013). "In order to determine whether an EGFR TKI or chemotherapy is the appropriate first-line therapy, guidelines recommend mutation testing for all patients with advanced NSCLC tumor and adenocarcinoma histology." (PMID 24364033, 2013). "Indeed, inhibitors for aurora kinases are effective against tumour cell lines that are refractory to EGFR inhibition." (PMID 23328114, 2013). "Thus, a response to cetuximab was detected in patients with undetectable tumor-specific EGFR expression, leading to the conclusion that the response to cetuximab is independent of EGFR expression in tumor tissue." (PMID 23824671, 2013). "We observed strong and selective binding of the fusion protein to EGFR-expressing tumor cells." (PMID 23573299, 2013). "However, the overactivation of EGFR participates in several essential tumorigenic mechanisms, such as tumor survival, invasion, angiogenesis, and metastatic spread." (PMID 24454509, 2013). "The mechanisms of action of EGFR antibodies against A431 cells in vivo are likely to involve a combination of Fab- and Fc-mediated effects depending on the antibody concentration at the tumour site." (PMID 23918228, 2013). "Inhibiting either IGF1R or EGFR results in activation of the reciprocal receptor, suggesting that combined inhibition of both pathways may yield enhanced tumor therapy." (PMID 24019942, 2013). "EGFR is known to be over-expressed in tumours of epithelial origin, including CRC." (PMID 23356214, 2013). "However, PI3K activation in tumor cells was shown to activate p38, which then stimulates EGFR and creates a positive feedback loop further activating PI3K." (PMID 24199173, 2013). "Even though some of the lung samples were aged more than a decade, we observed high detection efficiency with high numbers of signals, especially mutant signals, which might reflect high mRNA expression from amplified EGFR in the tumor." (PMID 24280411, 2013). "Phosphorylated EGFR is easily assessable and may be integrated along with other histological markers of tumor aggressiveness." (PMID 23819610, 2013). "One tumor, which was examined with laser capture microdissection and molecular biological tools, demonstrated an EGFR mutation but not a K-ras mutation." (PMID 24100939, 2013). "To determine whether EGFR antibodies had fully opsonized their target, we analysed target binding on the tumour cells recovered from the peritoneum identified by their CFSE signal." (PMID 23918228, 2013).
tumor (continued). "Also, activation of mitochondrial caspases, appearance of TUNEL positive cells as well as IHC results in DPDIM treated tumor tissues augmented our in vitro findings of apoptosis involving EGFR pathway inhibition." (PMID 23555785, 2013). "In vivo activity of IgA2 EGFR was tested in a long-term xenograft tumour model, using the human epidermoid cell line A431, transduced with a luciferase gene (A431-luc2) allowing longitudinal monitoring of tumour growth by bioluminescent imaging (BLI)." (PMID 23918228, 2013). "Among them, the affibody molecule, ZEGFR:1907, has been shown to specifically bind EGFR with no cross-binding to other growth factor receptors, as well as fast tumor targeting and excellent tumor-to-normal tissue contrast on EGFR-expressing xenografted epithelial cancer models." (PMID 23710458, 2013). "In NSCLCs, several T cell epitopes derived from mutated antigens were reported –, but there have been no reports on the tumor-specific neo-antigens derived from EGFR driver mutations." (PMID 24223798, 2013). "However, our results demonstrate that EGFR amplified tumor cells can be easily outgrown by another cell population, which in case of our xenograft model was a stromal cell population." (PMID 24349039, 2013). "Female gender (P = 0.072), tumor response (P = 0.005), and gefitinib treatment (P>0.001) were significantly more frequent in the group of patients with EGFR mutations, whereas other characteristics showed no inter-group differences." (PMID 23940741, 2013). "In CRC patients, we observed that, in the majority of the tumor samples with somatic EGFR mutations (91%), the total level of EGFR mRNA was not increased but, in contrast, decreased and this result was obtained using two independent methods." (PMID 23565769, 2013). "In addition to CD14-and TLR4-dependent LPS-signaling, activation of the EGFR seems to be a crucial element of the observed tumor cell proliferation." (PMID 22923191, 2013). "Thus, GBM tumor cell lines transfected with EGFR siRNA, Rictor siRNA, or the combination of both, were exposed in vitro to chemotherapeutic drugs commonly used in for treatment of patients with GBM including: irinotecan, vincristine and temozolomide." (PMID 23555046, 2013). "Our results demonstrated that LPEI/siRNA-EGFR complexes could downregulate EGFR expression in SPC-A1 xenografted tumor upon single i.p. injection." (PMID 27234384, 2013). "Despite these suboptimal conditions IgA2 EGFR elicited significant anti-tumour activity." (PMID 23918228, 2013). "In this situation, the resistance of tumor cells to EGFR inhibition results from the functional irrelevance of EGFR as opposed to the inability of these agents to inhibit basal or ligand-induced EGFR activity." (PMID 23935914, 2013). "Stat3 can be phosphorylated by activated EGFR and promote tumor survival in vivo in NSCLC." (PMID 23937717, 2013). "However, because EGFR mutation is considered to be a driver mutation for carcinogenesis, the presence of another driving factor to induce tumor cells with wild-type EGFR would be necessary, suggesting that this event would be very rare." (PMID 24369725, 2013). "Consequently, multiple therapeutic agents and strategies have been developed to block the strong tumor promoting effects exerted by EGFR." (PMID 24349829, 2013). "The degree of tumor differentiation (Edmondson grade) was significantly associated with expression of both EGFR and VEGFR2 (P = 0.003 and 0.004, respectively), which showed that well-differentiated HCC tended to express EGFR and VEGFR2 at high levels." (PMID 23785399, 2013). "Here we provide the first evidence that IgA2 EGFR can mediate potent anti-tumour effects in vivo." (PMID 23918228, 2013). "Moreover, stable, long-term expression of a dominant-negative EGFR leads to a mesenchymal to epithelial-like transition and induction of angiogenic tumor growth." (PMID 23429996, 2013).